DNAH2 (dynein axonemal heavy chain 2)
Description:
As part of the axonemal inner dynein arm complex plays a central role in ciliary beat. Expressed in sperm flagellum, it is required for sperm motility. Dyneins are microtubule-based molecular motors possessing ATPase activities that can convert the chemical energy of ATP into relative sliding between adjacent microtubule doublets to generate ciliary bending.
Synonyms: DNAHC2; DNHD3; KIAA1503; FLJ46675; SPGF45
Tractability: Small molecule: a structure with a bound ligand is known. PROTAC: ubiquitination databases record sites on it.
Gene: Protein-coding gene on chromosome 17 (7,717,744 to 7,833,742, forward strand). Ensembl gene ENSG00000183914.
Subcellular location: Cytoplasm, cytoskeleton, cilium axoneme; Cytoplasm, cytoskeleton, flagellum axoneme
Subcellular location (Human Protein Atlas): End piece; Flagellar centriole; Microtubules; Primary cilium; Basal body; Cytokinetic bridge; Mitotic spindle
Gene Ontology:
Molecular function: dynein intermediate chain binding; dynein light intermediate chain binding; microtubule motor activity; minus-end-directed microtubule motor activity; ATP binding
Biological process: cilium-dependent cell motility; inner dynein arm assembly; cilium movement involved in cell motility; microtubule-based movement
Cellular component: axoneme; inner dynein arm; motile cilium; sperm end piece; sperm flagellum; 9+2 motile cilium; axonemal dynein complex; dynein complex
Genetic constraint (gnomAD): Loss-of-function variants: 323 observed, 540.95 expected, observed/expected ratio (o/e) 0.6, 90% interval 0.54 to 0.65. The upper end of that interval is the gene's LOEUF score, 0.65, which puts it in group 2 of 6, group 1 being the genes least tolerant of losing a copy. Missense variants: 4,907 observed, 5,924.2 expected, observed/expected ratio (o/e) 0.83, 90% interval 0.81 to 0.85. Synonymous variants: 2,092 observed, 2,275.1 expected, observed/expected ratio (o/e) 0.92, 90% interval 0.89 to 0.95.
Homologues: Orthologues: chimpanzee DNAH2 (99% identical), macaque DNAH2 (96% identical), rabbit DNAH2 (93% identical), dog DNAH2 (91% identical), rat Dnah2 (91% identical), mouse Dnah2 (91% identical), pig DNAH2 (89% identical), guinea pig DNAH2 (89% identical), tropical clawed frog dnah2 (73% identical), zebrafish dnah2 (70% identical), Drosophila melanogaster kl-2 (46% identical). Paralogues in human: DNAH10 (33% identical), DNAH1 (33% identical), DNAH6 (32% identical), DNAH17 (31% identical), DNAH7 (31% identical), DNAH3 (31% identical), DNAH9 (31% identical), DNAH12 (31% identical), DNAH11 (31% identical), DNAH5 (30% identical), DNAH8 (30% identical), DNAH14 (27% identical), and 3 more.
Diseases named in the same sentence as DNAH2 in open-access papers:
DNAH2 is named in the same sentence as 20 diseases in open-access papers, as found by Europe PMC text mining. Sharing a sentence is not in itself a finding about the gene and the disease. The quoted sentences say what the papers report.
male infertility (7 papers, 2020 to 2024). The inability of the male to effect fertilization of an ovum after a specified period of unprotected intercourse. "To date, autosomal recessive mutations in DNAH2 have been associated morphological abnormalities of the sperm flagella responsible of male infertility." (PMID 36859317, 2023). "In summary, we identified a novel DNAH2 variant that segregated with male infertility in a consanguineous family of Pakistani origin." (PMID 33968937, 2021). "Only five DNAH2 variants, however, were reported to be pathogenic and cause male infertility with MMAF phenotypes in human." (PMID 33968937, 2021). "Using a mouse model, we found DNAH2 deficiency causes male infertility with MMAF phenotypes and aberrant protein expression of various structural components in sperm flagella." (PMID 33968937, 2021). "For example, mutations in IDA and ODA genes, such as DNAH1, DNAH2, DNAH8, and DNAH10, cause male infertility due to asthenozoospermia with multiple morphological abnormalities of the sperm flagella." (PMID 36726469, 2022). "Additionally, other DNAHs, such as DNAH1, DNAH2, DNAH8, DNAH10, DNAH12, and DNAH17, are suggested to be pathogenic genes of isolated male infertility." (PMID 39503742, 2024). "Mutations in two IDA heavy-chain protein-encoding genes, DNAH1 (MIM: 603332) and DNAH2 (MIM: 603333), and two ODA heavy chain components, DNAH8 (MIM: 603337) and DNAH17 (MIM: 610063), have been described in individuals with isolated male infertility due to asthenoteratozoospermia." (PMID 37424858, 2023). "Previous studies demonstrate pathogenic DNAH1 or DNAH2 variants cause male infertility and MMAF without obvious PCD symptoms." (PMID 33968937, 2021). "Four recessive (TRIOBP, SLC26A4, GJB2, COL4A3) and one dominant (SOX10) for the deafness; six recessive genes (LRGUK, DNAH9, ARMC4, DNAH2, RSPH6A, and ACE) for male infertility can be conclusively ascribed." (PMID 38884051, 2024).
clear cell renal cell carcinomas (3 papers, 2019 to 2022). "DNAH2 mutation was reported in Parkinson’s disease, autism, adult-onset hearing loss, and clear cell renal cell carcinomas." (PMID 32508873, 2020). "Increased incidence of non-synonymous single-nucleotide mutations and insertions/deletions was found in DNAH2, DNAH5, and DNAH10 genes of CpG-island methylator phenotype positive clear cell renal cell carcinomas." (PMID 35501919, 2022). "DNAH2, DNAH5 and DNAH10 have been reported to have an elevated incidence of nonsynonymous single-nucleotide mutations and indels in CIMP-positive clear cell renal cell carcinomas." (PMID 30944005, 2019).
Infertility (3 papers, 2021 to 2024). "A homozygous missense variant, (NM_020877.4: c.2479C>T: p.[Arg827Trp]) in DNAH2 was identified as a candidate variant for his infertility." (PMID 38884051, 2024). "It has been demonstrated that infertile males with variants in DNAH1, DNAH2, DNAH7, and DNAH8 have a favorable prognosis, while patients with variants in DNAH17 have poor outcomes after ICSI treatment." (PMID 39503742, 2024). "DNAH2 deficiency in mice causes male-specific infertility resembling MMAF sperm phenotypes, thus directly establishing DNAH2 as a causative gene to MMAF." (PMID 33968937, 2021).
Primary microcephaly (2 papers, 2024 to 2026). Head circumference below 2 standard deviations below the mean for age and gender at birth. "Consistent with the idea that dynein mutations may affect neurodevelopment in addition to fluid dynamics, mutations in the dynein gene DNAH2 have been previously reported in patients with primary microcephaly." (PMID 41596228, 2026). "Additionally, mutations in the genes Dnah2 and Dnah14, which contribute to motile cilia structure, have been associated with primary microcephaly, neurodevelopmental disorders, and other conditions such as seizures." (PMID 39594631, 2024).
Dextrocardia (1 paper, 2025). The heart is located in the right hand sided hemithorax. "As mentioned in the section on de novo candidate genes, both probands in our study carrying rare deleterious DNAH2 variants exhibited dextrocardia." (PMID 40406060, 2025). "Furthermore, two probands carrying the DNAH2 variant consistently presented with dextrocardia in their X-ray chest records, providing support for the hypothesis that abnormal DNAH2 gene function may play a role in CHD/LD development." (PMID 40406060, 2025).
Hydrocephalus (1 paper, 2023). Hydrocephalus is an active distension of the ventricular system of the brain resulting from inadequate passage of CSF from its point of production within the cerebral ventricles to its point of absorption into the systemic circulation. "In conclusion, we report novel mutations in known hydrocephalus genes in 18% of our PCH probands and propose three novel candidate genes: DNAH2, TIE1 and RNPC3 in a further 11%." (PMID 36859317, 2023). "Depletion of either Dnah2 or WD repeat domain 78 (Wdr78), another dynein f subunit, by RNAi in mouse ependymal cells resulted in increased incidence of paralyzed motile cilia, and interestingly, knockdown wdr78 zebrafish larvae displayed hydrocephalus." (PMID 36859317, 2023).
tumor (4 papers, 2021 to 2023). "Actually, tumor common mutated genes, like TTN, FAT4, and DNAH2, were highly altered in SMC5 mutation samples, respectively, with the alteration frequency of 100%, 88%, and 81% in COAD, and 100%, 89%, and 83% in READ." (PMID 35894836, 2023). "Interestingly, three genes of the dynein family of microtubule-associated motor proteins (DNAH2, DNAH3 and DNAH5) showed stopgain mutations in different post-chemotherapy residual tumor samples." (PMID 38254917, 2023). "Except for DNAH2 and BRCA2, all the other genes were shared by the two tumor stages." (PMID 33428592, 2021). "Similarly, DNAH2, a member of an axonemal dynein complex, is involved in motile cilia that plays a vital role in human development and homeostasis and is among the primary cilium-related genes that are enriched in both SHH and Group 3 tumours." (PMID 35008416, 2022).
DNAH2 also shares sentences with these, for which no sentence is quoted: asthenozoospermia (1 paper); autism (1); Azoospermia (1); colorectal cancer (1); deafness (1); Encephalocele (1); Huntington disease (1); medulloblastoma (1); neurodevelopmental disorder (1); Onset (1); Parkinson disease (1); psoriasis (1); teratozoospermia (1).